ANO6 (anoctamin 6)
Diseases named in the same sentence as ANO6 in open-access papers (continued):
Sharing a sentence is not in itself a finding about the gene and the disease.
cancer (19 papers, 2014 to 2026). A tumor composed of atypical neoplastic, often pleomorphic cells that invade other tissues. "Our data have also shown that Ano6-KD significantly attenuates ERK phosphorylation, which is implicated in the regulation of cancer cell proliferation by Ano1, suggesting that Ano6 is potentially involved in regulating myoblast proliferation through the ERK signaling pathway." (PMID 24663380, 2014). "Since the essential role of cancer immunology and immune therapy, we explored the possible impact of ANO6 on different immune cell types in the BC microenvironment." (PMID 37960776, 2023). "Cell death can be induced in cancer cells by activation of ANO6 through melittin-induced PLA2 or through lipid peroxidation." (PMID 30893776, 2019). "On the contrary, pronounced activation of ANO6 due to a large increase in intracellular calcium, activation of phospholipase A2 or lipid peroxidation, can lead to ferroptotic death of cancer cells." (PMID 30893776, 2019). "Ano6 deficiency significantly reduces ERK/AKT phosphorylation, which has been shown to be involved in regulation of cancer cell proliferation by another Anoctamin member." (PMID 24663380, 2014). "Interestingly, the inhibition of ANO6 blocks tumor growth by disrupting the delivery of exogenous cholesterol to cancer cells and reversing immune suppression." (PMID 38238671, 2024). "First, we have an overview of the ANO6 gene expression in pan-cancer and found a significant difference in ANO6 expression in various cancers compared with the normal group, indicating that ANO6 might be related to tumor occurrence." (PMID 37960776, 2023). "Activation of ANO6 is essential during ferroptosis mediated cancer cell death." (PMID 33947836, 2021). "They concluded that the activation of ANO6 might be an important component during ferroptosis cell death and induce cell death in cancer cells." (PMID 34222241, 2021). "While ANO5, ANO7, and ANO9 may also be relevant for growth of cancers, evidence has been provided for a role of ANO6 (TMEM16F) in regulated cell death." (PMID 30893776, 2019). "Moreover, GSEA showed that ANO6 was positively associated with focal adhesion, TGF-beta signaling pathway, ECM receptor interaction, propanoate metabolism, complement and coagulation cascades, and pathways in cancer." (PMID 37960776, 2023). "Thus, direct activation of ANO6 may be a promising new strategy to induce cell death in cancer cells." (PMID 30893776, 2019). "Thus, activation of anoctamins, particularly of ANO6, might be a possibility to induce cell death in cancer cells." (PMID 30893776, 2019). "Several proteins involved in carcinogenesis or leukemogenesis are increased for clinical responders (ANO6, CHI3L1, CTSG, ELANE and FGR), suggesting that the sensitivity to ATRA/VP additionally depends on more general functions involved in cancer development." (PMID 33946813, 2021). "There were significant differences in the distribution of histologic subtype and race between the 2 ANO6 expressers (P < .001), but age, gender, menopause status, and cancer stage in the low ANO6 group were not significantly different from those in the high ANO6 group (P > .05)." (PMID 37960776, 2023).
tumor (18 papers, 2018 to 2025). "ANO6, a calcium-activated chloride channel with phospholipid scramblase activity, likely facilitates efferocytosis by exposing phosphatidylserine (PS) on the outer membrane—a critical “eat-me” signal for tumor-associated macrophages (TAMs)." (PMID 40762681, 2025). "Moreover, ANO6 was notably correlated with immune checkpoint expression levels, and scores of tumor mutation burden and microsatellite instability (all P < .05)." (PMID 37960776, 2023). "Further in vivo experiments confirmed the regulatory role of ANO6 (TMEM16F) in GIST progression, as evidenced by the reduction in tumor volume and weights after ANO6-plasmid treatment." (PMID 38756246, 2024). "First, we determined the ANO6 (TMEM16F) expression levels in stromal tumor tissues and adjacent normal tissues." (PMID 38756246, 2024). "To further illustrate the mechanism by which ANO6 (TMEM16F) inhibited tumor growth in vivo, we determined the number of apoptotic cells in GIST." (PMID 38756246, 2024). "Our data revealed that ANO6 (TMEM16F) was expressed at low levels in stromal tumor tissues from patients with GISTs compared to those in adjacent normal tissues, indicating that ANO6 (TMEM16F) is related to the progression of GIST." (PMID 38756246, 2024). "In gastrointestinal stromal tumors (GISTs), ANO6 is found to be downregulated, and its overexpression inhibits tumor growth." (PMID 39534397, 2024). "Aberrant expression of ANO6 is involved in tumour metastasis and is closely correlated with ERK signalling activation." (PMID 37076508, 2023). "JUN presented low-expression in both normal and tumor tissues, whereas ANO6 presented high-expression." (PMID 34715817, 2021). "These interactions suggest a coordinated mechanism: ANO6-mediated ion dyshomeostasis primes early metastatic niche formation, while PLGRKT loss exacerbates ECM stiffness and inflammatory signaling, collectively fueling tumor progression." (PMID 40762681, 2025). "ANO6 exerts its anti-tumor effects by inducing cell death through ferroptosis." (PMID 39534397, 2024). "In addition, reduced Cys, GSH, and GPX4 expression levels were observed in ANO6-plasmid treated xenograft tumor models." (PMID 38756246, 2024). "Therefore, ANO6 has potential significance in tumor immunity." (PMID 34901006, 2021). "Our analysis of differential expression indicated that ANO6 and IL33 were markedly downregulated in cancerous tissues relative to normal ones, whereas SIAH2 showed elevated expression in tumor samples." (PMID 39911848, 2025). "Integrated analysis of GTEx (normal, n = 171) and TCGA (tumor, n = 179) datasets revealed higher expression of CHST11, SLC16A1, RHOF, MAN1C1, SPRR1B, and ANO6 in tumors." (PMID 41346619, 2025). "The levels of ANO6 (TMEM16F) were remarkably lower in the stromal tumor tissues of patients with GIST than in the adjacent normal tissues, indicating a regulatory role of ANO6 (TMEM16F) in GIST." (PMID 38756246, 2024). "These genes are paralogs of XKR8 and ANO6/TMEM16F, which mediate an externalization of phosphatidyl serine, creating an immunosuppressive tumor micro environment." (PMID 30429477, 2018).
renal disease (2 papers, 2018 to 2023). "The Cl−-transporting proteins CFTR, SLC26A9, and anoctamin (ANO1; ANO6) appear to have more in common than initially suspected, as they all participate in the pathogenic process and clinical outcomes of airway and renal diseases." (PMID 37686084, 2023).
ANO6 also shares sentences with these, for which no sentence is quoted: virus infection (7 papers); COVID-19 (3); infection (3); ischemic stroke (3); thrombosis (3); Alzheimer disease (2); Cerebral ischemia (2); HIV-1 infection (2); ischemia (2); lymphoma (2); melanoma (2); muscular dystrophy (2); neuroblastoma (2); neurodegenerative disease (2); pancreatic cancer (2); Renal cyst (2); Stroke (2); tauopathy (2); AIDS (1); ankylosing spondylitis (1); Arthritis (1); atherosclerosis (1); autoimmune disease (1); autosomal dominant polycystic kidney disease (1); autosomal recessive spinocerebellar ataxia (1); bacterial infection (1); cerebral edema (1); cervical cancer (1); colon cancer (1); deafness (1).
A further 29 diseases each share a sentence with ANO6 in 1 paper.